ENSG00000267881 (novel protein, readthrough between CEACAM5-CEACAM6)
Gene: Protein-coding gene on chromosome 19 (41,708,657 to 41,756,737, forward strand). Ensembl gene ENSG00000267881.
Genetic constraint (gnomAD): Loss-of-function variants: 2 observed, 3.39 expected, observed/expected ratio (o/e) 0.59, 90% interval 0.24 to 1.65. That is too few expected variants to judge how well the gene tolerates losing a copy. Missense variants: 81 observed, 85.25 expected, observed/expected ratio (o/e) 0.95, 90% interval 0.79 to 1.14. Synonymous variants: 32 observed, 34.16 expected, observed/expected ratio (o/e) 0.94, 90% interval 0.71 to 1.26.